IL6 (interleukin 6)
Diseases named in the same sentence as IL6 in open-access papers (continued):
Sharing a sentence is not in itself a finding about the gene and the disease.
signet ring cell carcinoma (2 papers, 2013 to 2023). A usually aggressive, poorly differentiated invasive adenocarcinoma characterized by the presence of malignant glandular cells in which the nucleus is pressed to one side by the presence of intracytoplasmic mucus. "Well-differentiated adenocarcinomas tended to express IL-6 in the stroma, whereas poorly differentiated adenocarcinomas and signet ring cell carcinomas were often positively stained in the tumor cells, although this tendency was not statistically significant." (PMID 23593346, 2013).
skin toxicities (2 papers, 2022 to 2025). "In individuals with EGFRI-induced skin toxicities, the levels of various inflammatory cytokines are increased, including IL6, TNFα, and CCL2." (PMID 35324426, 2022).
somatotropinomas (2 papers, 2019 to 2023). "In somatotropinomas, the transforming growth factor (TGF)-α and the TGF-β1 stimulate the tumor secretion of IL-6." (PMID 36658300, 2023). "NF-PitNETs were more often secreting IL-8, CCL2, CCL4, IL-6 and PDGF-AA than somatotropinomas." (PMID 31703742, 2019).
spinal tuberculosis (2 papers, 2021 to 2025). "To investigate this further, we collected blood samples from patients with spinal tuberculosis and assessed the concentrations of IL-6 and TNF-α." (PMID 40396181, 2025). "In conclusion, Dex may have anti-inflammatory actions and can reduce the release of TNF-α and IL-6 in spinal tuberculosis patients during the perioperative period." (PMID 33679943, 2021). "The results revealed a significant upregulation of serum concentrations of IL-6 and TNF-α in patients with spinal tuberculosis compared to healthy controls." (PMID 40396181, 2025).
spondylitis (2 papers, 2020 to 2022). The inflammation of a vertebra. "Correlation between DNA methylation of SOCS1 and the degree of inflammation, assessed by TNFα and IL-6 levels, was also shown in patients with HLA-B27+ spondylitis." (PMID 32670294, 2020).
spondylolisthesis (2 papers, 2024 to 2026). A condition in which there is forward displacement of a vertebral bone over the on below it. "Mediation analyses identified 13 genetically supported putative GM-IPs-DLSD pathways, highlighting convergent mediators including PD-L1 for spondylolisthesis and IL-6 and IL-18 for IDD, with mediation proportions ranging from 7.55% to 13.22% across key pathways." (PMID 42317351, 2026). "IP MR identified risk-increasing associations for LSS (4E-BP1 and interleukin-4), spondylolisthesis (CXCL1, CXCL5, FGF-5, IL-15RA, and IL-4) and IDD (IL-20RA and IL-6), while IL-18 showed a protective association with IDD that remained robust after multiple-testing correction." (PMID 42317351, 2026).
systolic heart failure (2 papers, 2009 to 2024). Heart failure caused by abnormal myocardial contraction during systole leading to defective cardiac emptying. "In patients with systolic heart failure, IL-6 and TNF-α are associated with functional NYHA class." (PMID 19909503, 2009). "There were statistically significant reductions in serum levels of IL-6 and hsCRP with an eight-week yoga-based program in patients with compensated systolic heart failure (HF) group (all p < 0.005 vs. medical therapy)." (PMID 38707001, 2024).
T cell deficiency (2 papers, 2022 to 2023). "In fact, immunocompromised rats tend to compensate their T-cell deficiency by means of a macrophage-induced overproduction of inflammatory cytokines, such as IL-6, which is crucially needed to promote T-cell proliferation and differentiation." (PMID 37760151, 2023). "Furthermore, T cell deficiency led to a reduction in plasma cytokines, including IL-6 and G-CSF." (PMID 35945238, 2022).
TB meningitis (2 papers, 2023). "Elevated IL-6 expression was also reported in pleural fluid of TB patients as well as in cerebrospinal fluid (CSF) in patients with TB meningitis." (PMID 37653422, 2023).
temporomandibular joint disorder (2 papers, 2025). Any condition affecting the anatomic and functional characteristics of the temporomandibular joint. "The COMT, HTR2A, MMPs, IL-1β, IL-6, TNF-α and ESR1 are known to influence the pain perception, inflammation, and joint integrity in temporomandibular joint disorders." (PMID 40291793, 2025).
teratoma (2 papers, 2017 to 2022). A non-seminomatous germ cell tumor characterized by the presence of various tissues which correspond to the different germinal layers (endoderm, mesoderm, and ectoderm). "In addition, IL-6 was high (1.602 pg/ml) in a single mouse at day 28, in which a teratoma was developed." (PMID 28220117, 2017).
Testicular atrophy (2 papers, 2013 to 2024). Wasting (atrophy) of the testicle (the male gonad) manifested by a decrease in size and potentially by a loss of fertility. "However, inhibition of IL-6 signaling through an IL-6 receptor antibody attenuated the decrease in testosterone and testicular atrophy in mice initiating weight loss." (PMID 24285707, 2013).
testicular germ cell tumor (2 papers, 2022 to 2025). A germ cell tumor arising from the testis. "In testicular germ cell tumor models, TG7 silencing led to reduced viability and upregulation of IL6 and TNFα, suggesting that TG7 might suppress apoptotic or inflammatory signals under physiological conditions." (PMID 41425727, 2025).
thrombotic thrombocytopenic purpura (2 papers, 2021 to 2026). "She received hemodialysis three times, a plasma exchange, and anti-interleukin-6 therapy to treat severe renal dysfunction, a thrombotic thrombocytopenic purpura-suspected condition, and possible grade 4 CRS, respectively." (PMID 33996612, 2021).
tongue tumor (2 papers, 2022). "To further validate the association between Fusobacterium burden and inflammation, we evaluated the levels of pro-inflammatory cytokines IL1B, IL8 and IL6 in Fusobacterium-high and -low in-house early-stage tongue tumor samples (n = 75)." (PMID 35252868, 2022). "We validate the association of Fusobacterium with the inflammatory markers IL1B, IL6 and IL8, miRNAs hsa-mir-451a, hsa-mir-675 and hsa-mir-486-1, and MMP10 in the tongue tumor samples." (PMID 35252868, 2022).
treatment resistant depression (2 papers, 2018 to 2023). Unipolar depression that does not respond to commonly used treatments, typically defined as lack of response to at least two appropriate antidepressant treatments. "There is also some evidence that treatment-resistant depression (TRD) is characterized by specific immune biomarkers, including increased IL-6, sIL-1RA, and TNFα concentrations." (PMID 29103192, 2018).
Turner syndrome (2 papers, 2010 to 2017). Turner syndrome is a chromosomal disorder associated with the complete or partial absence of an X chromosome. "Eight TFs and four ERFs are among the differentially expressed genes, as well as eight genes associated with Turner syndrome (PROCR, NR3C1, INSR, APOB, BMP15, F8, IL6, and WAS) and two genes that are haploinsufficient in humans (RAD50 and SLC33A1)." (PMID 28818098, 2017). "Moreover the dose effect in Turner syndrome group is equivalent to that of males as median IL6 production is also dampened with the higher LPS concentration of 1 ng/ml compared to 0.2 ng/ml (p < 0.004: paired Wilcoxon)." (PMID 20525175, 2010).
type 1 Gaucher disease (2 papers, 2016 to 2017). "Consistent with our results, macrophages derived from peripheral monocytes from patients with type 1 Gaucher disease with genotype N370S/N370S showed an increased secretion of interleukins IL-1β and IL-6." (PMID 28166796, 2017). "Studying macrophages derived from peripheral monocytes from patients with type 1 Gaucher disease with genotype N370S/N370S, we confirmed an increased secretion of interleukins IL‐1β and IL‐6." (PMID 26486234, 2016).
Type A Aortic Dissection (2 papers, 2020 to 2022). "In addition, there were time-dependent changes in plasma inflammatory biomarkers including hs-CRP and IL-6 in type A aortic dissection patients." (PMID 32034642, 2020).
Ureaplasma infection (2 papers, 2012 to 2023). "Others have demonstrated that intra-amniotic ureaplasma infection did not result in increased levels of any tested cytokines (IL-1β, IL-1 receptor antagonist, IL-4, IL-6 and TNF-α)." (PMID 22253806, 2012).
uterine disease (2 papers, 2014 to 2025). "Gene transcripts for IL6 and IL8 are more abundant in the endometrium of cattle with uterine disease than in normal animals and in endometrial explants treated with heat-killed Gram-positive bacteria or bacterial lipopeptides." (PMID 24437488, 2014).
valvular heart disease (2 papers, 2011 to 2017). "In conclusion, TLR2, independent of IL-6, was up-regulated in AF (especially PaAF) patients with valvular heart disease, which further implicates inflammation in the pathogenesis and development of AF." (PMID 23554687, 2011).
vascular neoplasm (2 papers, 2014 to 2024). A benign, intermediate, or malignant neoplasm arising from vascular tissue including arteries, veins, venous sinuses, lymphatic vessels, arterioles and capillaries. "Furthermore, IL-6 stimulates the expression of vascular epithelial growth factor (VEGF), causing vascular proliferation, which is thought to be of great importance in the development of vascular neoplasms in CD." (PMID 24649966, 2014). "IHC scores of CXCL1、CXCL2、IL6、ABCC1、LRP、BCL2, vascular tumor thrombus, ascites cancer cells, maximum tumor diameter, neoadjuvant chemotherapy, and HE4 were included in the prediction model." (PMID 38509620, 2024). "As predictors, the immunohistochemical scores of CXLC1, CXCL2, IL6, ABCC1, LRP, BCL2, vascular tumor thrombus, ascites cancer cells, maximum tumor diameter, neoadjuvant chemotherapy, and HE4 were employed." (PMID 38509620, 2024). "Finally, the immunohistochemical scores of CXLC1, CXCL2, IL6, ABCC1, LRP, BCL2, vascular tumor thrombus, ascites cancer cells, maximum tumor diameter, neoadjuvant chemotherapy, and HE4 were employed." (PMID 38509620, 2024).
viral respiratory tract infection (2 papers, 2006 to 2025). A respiratory tract infection caused by a virus. "Whilst IL-6 has not been shown to be directly antiviral, IL-6 can stimulate endothelial cells to release IL-8, and therefore can contribute to the neutrophilic infiltration observed in viral respiratory tract infections." (PMID 16670028, 2006).
vitamin A deficiency (2 papers, 2004 to 2023). Deficiency of vitamin A due to malnutrition, malabsorption, or dietary lack. "In the mouse model of vitamin A deficiency, supplementation of β-carotene also downregulated the levels of intestinal inflammatory cytokines, TNFα, IL1-β, and IL-6, and immunomodulatory cytokines, IL22, IL23, and IL17." (PMID 37018237, 2023). "The relationship between IL-6 and elevated acute phase proteins has not well been characterized in epidemiological studies of vitamin A deficiency." (PMID 15588289, 2004).
Werner syndrome (2 papers, 2016). "Mice carrying a Werner Syndrome (WS) mutation and a simultaneous knockdown of the RecQ-type DNA helicases exhibited an increased inflammatory status characterized by expression changes in HIF-1, IL-6, and components of the NFκB pathway." (PMID 27555866, 2016).
Acanthamoeba keratitis (1 paper, 2022). Keratitis due to infection by acanthamoeba; it is usually associated with soft contact lens wear, particularly overnight wear. "IL-1α, IL-2, IL-6, IL-10, IL-12, IL-17, IL-18, and IL-23 have roles in viral keratitis and IL-17 in Acanthamoeba keratitis." (PMID 36422638, 2022).
acquired long QT syndrome (1 paper, 2018). A form of long QT syndrome in which malfunction of the cardiac ion channels is caused by drugs or metabolic abnormalities. "Increased proinflammatory interleukin-6 (IL-6) levels are associated with acquired long QT-syndrome (LQTS) in patients with systemic inflammation, leading to higher risks for life-threatening polymorphic ventricular tachycardia such as Torsades de Pointes." (PMID 30521586, 2018).
actinic keratosis (1 paper, 2021). A precancerous lesion of the skin composed of atypical keratinocytes. "Further, the levels of secreted IL-6 and IL-8 protein in response to S. aureus secretomes from HaCaT keratinocytes was comparable to those observed for primary human keratinocytes, isolated from normal skin and actinic keratosis." (PMID 35145494, 2021).
acute conjunctivitis (1 paper, 2013). Acute inflammation of the conjunctiva. "In conclusion, we have examined the effects of azithromycin on the LPS-induced acute conjunctivitis model in rats, and we found evidence that topical azithromycin inhibits the expression of inflammatory cytokines such as IL-6, MMP-2 activity, and NF-κB." (PMID 23378729, 2013).
acute diarrheal disease (1 paper, 2024). "However, research on IL-6 and IL-8 as biomarkers in acute diarrheal disease is limited." (PMID 39062898, 2024). "Furthermore, one study conducted on children with acute diarrheal disease caused by rotavirus brought to light that most of the patients (more than 70%) presented no positivity of serum IL-6." (PMID 39062898, 2024).
acute thyroiditis (1 paper, 2014). Acute form of thyroiditis (disease). "Experiments have shown that IL-6 concentrations in plasma are high in patients with sub-acute thyroiditis." (PMID 25226272, 2014).
adrenocortical tumour (1 paper, 2021). "The use of the adrenocortical tumour ATC7 cell line with complete zona fasciculata cell phenotype enabled us to assess the effect of an inflammatory stimulus on the expression of the pro-inflammatory cytokine IL-6 mRNA and the expression of key steroidogenic genes." (PMID 33571577, 2021).
agoraphobia (1 paper, 2015). An anxiety disorder characterized by an intense, irrational fear of venturing out into open places or situations in which help (or escape) might not be available should excessive anxiety or panic symptoms develop. "Associations between lifetime agoraphobia status at baseline and inflammatory measures (interleukin-6) at follow-up, serially adjusted for covariates." (PMID 25875094, 2015). "The direction of the association between agoraphobia and IL-6 was also as hypothesized direction, although the association was not significantly, suggesting insufficient statistical power." (PMID 25875094, 2015). "The composite score of proinflammatory markers (including CRP, IL-6 and TNF-α) at follow-up was higher (model 5: β = 0.578 (95%-CI 0.241–0.915) among subjects suffering from lifetime agoraphobia at baseline." (PMID 25875094, 2015).
alcohol addiction (1 paper, 2023). "Taken all together, the association revealed from our study regarding IL6 rs1800795 and alcohol addiction is of great interest." (PMID 38275640, 2023). "We found a statistically significant association of IL6 rs1800795 with alcohol addiction after a comparison of the genotype frequencies of alcohol-addicted patients and healthy individuals, which remained significant after adjustments for other parameters associated with alcohol addiction." (PMID 38275640, 2023). "Our data revealed that IL6 rs1800795 may play some role in the susceptibility to alcohol addiction, as well as that the genetic variation of both the oxidative stress and inflammation pathways potentially impact the psychosymptomatology of alcohol-addicted patients and healthy individuals." (PMID 38275640, 2023). "However, to our knowledge, there are no studies that focus on the genetic variability of PON1, SOD2, GPX1, IL1B, IL6, interleukin 6 receptor (IL6R), and miR146a related to the risk of alcohol addiction, and patients’ comorbid psychosymptomatology." (PMID 38275640, 2023). "Our findings suggested the involvement of IL6 rs1800795 in alcohol addiction." (PMID 38275640, 2023). "Thus, we focused on the role of PON1 rs705379, rs705381, rs854560, and rs662, SOD2 rs4880, GPX1 rs1050450, IL1B rs1143623, rs16944, and rs1071676, IL6 rs1800795, IL6R rs2228145, and miR146a rs2910164 in alcohol addiction, and patients’ comorbid psychosymptomatology." (PMID 38275640, 2023).
alcoholic pancreatitis (1 paper, 2021). Acute or chronic inflammation of the pancreas due to excessive alcohol drinking. "Further study should be performed to determine the effect of lycopene on NADPH oxidase activity, ROS levels, mitochondrial function, NF-κB activity, IL-6 expression, and zymogen activation in pancreatic tissues using in vivo alcoholic pancreatitis models." (PMID 33672594, 2021).
Alexander disease (1 paper, 2022). Alexander disease (AxD) is a rare neurodegenerative disorder of the astrocytes comprised of two clinical forms: AxD Type I and Type II manifesting with various degrees of macrocephaly, spasticity, ataxia and seizures and leading to psychomotor regression and death. "Ablation of caspase-6 is correlated with low levels of the pro-inflammatory cytokines TNF-α and IL-6 and astroglial cl-caspase-6 has been found in brain samples of patients with Alzheimer’s and Alexander’s disease." (PMID 36347836, 2022).
Alopecia universalis (1 paper, 2024). Alopecia universalis is the most severe form of alopecia areata, an inflammatory disease of the hair follicle, which is characterized by a complete loss of hair of the scalp and all the hair-bearing areas of the body. "Another case report described a paradoxical increase in cytokines, including IL-4, IL-6, IL-10, IFN-γ, and IL-17, after six months of Tofacitinib treatment in a patient with alopecia universalis." (PMID 39850156, 2024).
altitude sickness (1 paper, 2023). Multiple symptoms associated with reduced oxygen at high altitude. "Plasma levels of IL-1β, IL-6, and TNF-α were found to be increased in individuals with altitude sickness compared to controls in low-altitude environments." (PMID 36891263, 2023).
anal prolapse (1 paper, 2022). "Reduces anal prolapse, surrounding hyperemia by decreasing MPO activity, serum IL-1β, IL-6, TNF-α levels, and increasing IL-4, IL-10 levels." (PMID 35548468, 2022).
Anaplasma phagocytophilum infection (1 paper, 2024). "Anaplasma phagocytophilum infection leads to the upregulation of pro-inflammatory cytokines TNF-α, IL-1, MIP-2, and IL-6." (PMID 39770719, 2024).
angiomatoid fibrous histiocytoma (1 paper, 2023). "Excessive production of IL-6 by the neoplastic cells of angiomatoid fibrous histiocytoma represents the major factor responsible for its associated paraneoplastic symptoms." (PMID 36690805, 2023).
aniridia (1 paper, 2025). Aniridia is a congenital ocular malformation characterized by the complete or partial absence of the iris. "Unlike the healthy counterpart, within their respective AN-LFC group the mut-LSCs-CM did not significantly increase the gene or protein expression of IL-6, a putative cytokine that promotes stemness, suggesting an aberrant interaction in congenital aniridia." (PMID 40622913, 2025).
ankylosis (1 paper, 2019). Fixation and immobility of a joint. "The effect of anti-IL-6 treatment in patients with ankylosing spondylitis has also been reported — studies revealed that the anti-IL-6 receptor antibody did not prevent the progression of spinal changes associated with ankylosis." (PMID 31200688, 2019). "However, histological investigations confirmed that entheseal ossification and ankylosis progressed even with IL-6 blockade treatment." (PMID 31200688, 2019).
aortic disorder (1 paper, 2019). Pathology involving the thoracic, thoracoabdominal, or abdominal aorta (including aneurysms). "The authors stated that theelevated serum IL-6 level observed in this patient might be a cause of theoccurrence of aortic disorders." (PMID 31112020, 2019).
Aphasia (1 paper, 2025). An acquired language impairment of some or all of the abilities to produce or comprehend speech and to read or write. "The relationship between cardiovascular disease history, treatment window, intraoperative blood loss, thrombectomy time, neutrophil percentage, aphasia symptoms, CRP, IL-6, IL-10 and recurrence degree is not significant." (PMID 40917676, 2025).